GIP (gastric inhibitory polypeptide)
Diseases named in the same sentence as GIP in open-access papers (continued):
Sharing a sentence is not in itself a finding about the gene and the disease.
Hypoglycemia (continued). "One proposed mechanism is related to the observation that patients with post-RYGB hypoglycemia have significantly higher levels of glucose-dependent insulinotropic polypeptide (GIP) and glucagon-like peptide-1 (GLP-1), both of which exert a hypertrophic effect on the pancreatic islet cells." (PMID 40395710, 2025). "As demonstrated in isolated rat islets, and later confirmed in human studies [103,], GIP has negligible effects on insulin secretion under conditions of hypoglycemia, but strongly potentiates insulin secretion when circulating glucose levels reach or exceed 6–8 mmol/l." (PMID 40024571, 2025). "GIP-mediated increase in circulating glucagon concentrations has been detected also in healthy humans, similar to preclinical studies this effect is glucose dependent, as it has been shown to occur only under hypoglycemia." (PMID 37729025, 2023). "It has been shown that GIP stimulates insulin release to exert hypoglycemic effects under hyperglycemic conditions, while stimulating glucagon secretion to reduce the occurrence of hypoglycemia in hypoglycemic states." (PMID 36119737, 2022). "When GIP levels therefore are elevated, as during DPP-4 inhibition, the glucagon counter-regulation to hypoglycemia may be supported by the action of GIP." (PMID 31275243, 2019). "This analysis also suggests that the activators of GLP-1, GIP and FFA receptors may have a relatively low risk of hypoglycemia in fasting conditions whereas an activator of muscarinic receptors can increase this risk." (PMID 27138453, 2016). "In health glucose-dependent insulinotropic polypeptide (GIP) is a potent glucose-lowering peptide that does not cause hypoglycaemia." (PMID 25613747, 2015). "Thus, during insulin-induced hypoglycemia, glucagon secretion is increased due to GIP use." (PMID 35630534, 2022). "Therefore, the increase in intact GIP levels observed after inhibition of DPP4 may help maintain the counter-regulatory response of glucagon when glucose levels are controlled at hypoglycemia." (PMID 35630534, 2022). "Thus, GIP is known to stimulate glucagon secretion during hypoglycemia." (PMID 31275243, 2019). "Our theoretical analysis shows that activators of GLP-1, GIP and FFAR1/GPR40 receptors may have a low risk of hypoglycemia because they need a concomitant increase in [Ca2+]c for activation whereas an activator of muscarinic receptors can lead to hypoglycemia." (PMID 27138453, 2016). "Importantly, the effects of GLP-1 and GIP are glucose dependent, so that exogenous administration of GLP-1 and/or GIP, even at pharmacological doses, does not cause hypoglycaemia." (PMID 25613747, 2015). "Both GLP-1 and glucose-dependent insulinotropic polypeptide (GIP) can stimulate pancreatic beta cells to secrete insulin in a glucose-dependent manner to control blood glucose levels, with hypoglycemia occurring very rarely as an adverse effect." (PMID 36831491, 2023). "Tirzepatide as the first dual GIP and GLP-1 RA drug, which shown effects on hypoglycemia, body weight and cardiovascular indicators in previous studies." (PMID 37141329, 2023). "In other studies following RYGB individuals with post-RYGB hypoglycaemia had greater postprandial GLP-1 and insulin concentrations but not GIP when compared with individuals who had the same bariatric surgery but did not develop hypoglycaemia." (PMID 38546831, 2024). "In fact, while GLP-1 constantly inhibits glucagon secretion, GIP has a bi-directional effect: it stimulates glucagon secretion only under conditions of normoglycemia and hypoglycemia, but not in the presence of hyperglycemia." (PMID 37729025, 2023). "Tirzepatide, a dual GIP/GLP-1R agonist, demonstrated robust reductions in glycaemic control and body weight for the patients in the SURPASS studies, without causing hypoglycaemia." (PMID 35949358, 2022).
Hypoglycemia (continued). "Fat ingestion is also a strong stimulant of GIP release, but in the state of eu- or hypoglycemia, GIP does not influence insulin, but stimulates glucagon secretion, suggesting that GIP supports the maintenance of optimal glucose levels." (PMID 32069846, 2020). "In humans, neither GLP-1 and GIP undergo much change in response to hyperinsulinemia-induced hypoglycemia." (PMID 24594704, 2014). "The use of a GLP-1 receptor blocker corrected postprandial hypoglycemia in patients who underwent gastric bypass, indicating that GIP does not play a major role in the mechanism of hypoglycemia, which instead appears to be driven primarily by the increased GLP-1 activity." (PMID 39994634, 2025). "Interestingly, direct glucagonotropic effects of GIP have been reported during hypoglycemia and euglycemia, but not hyperglycemia, unless there was underlying metabolic disease." (PMID 32964214, 2020). "Interestingly, GIP is known to stimulate glucagon secretion in hypoglycemia and not influence glucagon secretion in hyperglycemia." (PMID 31781045, 2019). "It increases the physiological concentration of glucagon like peptide GLP-1 and glucose dependent insulinotropic polypeptide (GIP) in body by inhibiting the enzyme dipeptidyl peptidase –IV (DPP-4) with well tolerated profile, no risk of weight gain and hypoglycemia." (PMID 28083033, 2016). "Furthermore, the relatively high incidence of hypoglycemic episodes may suggest that the GIP component is not active and therefore does not protect against hypoglycemia." (PMID 31443356, 2019). "Plasma CTX concentrations were consistently reduced by GIP under all glycemic conditions, whereas P1NP levels showed only a transient increase under hypoglycemia and no sustained differences from saline." (PMID 41596254, 2026). "Individuals who had post-bariatric surgery hypoglycaemia had greater postprandial GLP-1 and insulin concentrations, but GIP responses were not different, when compared with individuals who had the same type of bariatric surgery but who did not develop hypoglycaemia." (PMID 37439960, 2023).
Hyperinsulinemia (25 papers, 2014 to 2026). An increased concentration of insulin in the blood. "GIP administration to lean, healthy humans during hyperinsulinemia causes a four-fold increase in blood flow and TG clearance in subcutaneous abdominal AT when compared to saline controls." (PMID 38579777, 2024). "Recent studies suggest that dietary amino acids can promote GIP secretion, enhancing post‐prandial [insulin]; this may increase the risk of hyperinsulinemia following consumption of high‐protein meals in horses with ID." (PMID 39836076, 2025). "A greater rise in IR-GIP following ingestion of a test meal was also observed in people with chronic pancreatitis, which led to the hypothesis that GIP hypersecretion may originate from the loss of a pancreatic feedback loop that normally inhibits GIP secretion under conditions of hyperinsulinemia." (PMID 40024571, 2025). "In summary, GIP promotes triglyceride storage under conditions of hyperinsulinemia, but enhances lipolysis and fatty acid oxidation under conditions of normo- or hypoinsulinemia." (PMID 40024571, 2025). "Conclusions and Clinical Importance: Horses with experimentally‐induced ID displayed significantly greater GIP responses to a high‐protein meal than at baseline, suggesting that GIP plays a role exacerbating post‐prandial hyperinsulinemia in this context." (PMID 39836076, 2025). "In addition, GIP potentiates insulin secretion from pancreatic β-cells as an incretin and thus plays an important role in hyperinsulinemia under HFD-feeding obese condition." (PMID 31977316, 2020). "The finding of increased GIP and insulin in the plasma of rotenone-treated rats suggests that the elevated level of GIP might have been responsible for the upregulation of insulin called hyperinsulinemia." (PMID 39851552, 2025). "RF led to the synchronization of the circadian rhythms in the insulin of the hormones, glucagon-like peptide-1 (GLP-1), glucose-dependent insulinotropic polypeptide (GIP), and hyperinsulinemia in the light period." (PMID 36557311, 2022). "Inflammatory stimuli, such as IL-6, TNFα, and endotoxin, induce GIP and GLP-1 secretion, leading to hyperinsulinemia in critically ill patients." (PMID 31126070, 2019). "The anastomosis of the feed loop to pre-pyloric antrum aims to reassume normalintestinal transit promoting change of the enteroinsular axis diminishing GIP and GLP-1and hence hyperinsulinemia." (PMID 26734801, 2015). "Interestingly, levels of several hormonal peptides related to hyperinsulinemia, such as insulin, leptin, pancreatic peptide (PP), peptide YY (PYY), and gastric inhibitory polypeptide (GIP), were significantly upregulated." (PMID 39851552, 2025). "Several studies further report decreased GIP secretion in response to oral nutrient ingestion under conditions of hyperinsulinemia, but this is not confirmed by other studies." (PMID 40024571, 2025). "However, while several studies support the notion that hyperinsulinemia attenuates the rise in plasma GIP following oral ingestion of glucose, this is not supported by other studies." (PMID 40024571, 2025). "Hence, the secretion of GIP and GLP‐1 may be of greater relevance as a compensatory mechanism in the latter group and contribute to hyperinsulinemia." (PMID 25413324, 2014). "Thus, GIP is unlikely to explain glucose-induced hyperinsulinemia." (PMID 24489924, 2014).
atherosclerosis (24 papers, 2012 to 2025). A disease characterized by the build-up of fatty material and calcium deposition in the arterial wall resulting in partial or complete occlusion of the arterial lumen. "Investigating the underlying mechanisms and clinical implications of GIP in atherosclerosis management is essential." (PMID 39493783, 2024). "GIP may play an indirect role in the development of atherosclerosis through the regulation of inflammation caused by macrophages, the formation of foam cells, the proliferation of SMC, and the remodeling of arteries." (PMID 37623488, 2023). "However, it has also been shown that increased plasma levels of GIP are associated with atherosclerosis in humans." (PMID 37592302, 2023). "Apart from having beneficial effects on atherosclerosis, GIP is also reported to protect from the detrimental effects of arterial remodeling after endothelial injury." (PMID 40024571, 2025). "Despite the variable precision of measuring fasting GIP, elevated levels of fasting GIP correlate positively with subclinical atherosclerosis in humans." (PMID 40024571, 2025). "Individuals with peripheral artery disease often have elevated levels of circulating GIP, a vascular protective peptide known to delay atherosclerosis progression." (PMID 39493783, 2024). "GIP infusion decreased resistin levels, an adipokine involved in inflammation and atherosclerosis in a similar way to sitagliptin, suggesting that DPP-4 inhibition produced by sitagliptin provides beneficial effects through the mediation of GIP." (PMID 36834796, 2023). "DPP-4 inhibitors were reported to have suppressive effects on atherosclerosis development and progression as a response to increased serum levels of GIP and GLP-1." (PMID 36834796, 2023). "The investigators demonstrated that myocardial infarction was associated with an increased resistin (an adipokine known to be correlated with inflammation and atherosclerosis) expression via the GIP-dependent pathway." (PMID 35205155, 2022). "Regarding the atherosclerosis effects of GIP in monotherapy, studies have also pointed to both the anti-atherogenic and pro-atherogenic effects of GIPR agonists." (PMID 36145148, 2022). "In alignment with this, a direct anti-inflammatory role for GIP in macrophages has also been suggested in the context of atherosclerosis, as well as in microglia in neurodegenerative disorders of the central nervous system." (PMID 33717200, 2021). "GIP plays an important role in the regulation of glucose and lipid metabolism and protects vessels from atherosclerosis." (PMID 29765988, 2018). "In a recent study by our group, however, GIP infusion suppressed the development of atherosclerosis in streptozotocin (STZ)-induced Apoe−/− mice." (PMID 23967137, 2013). "On the other hand, the action of Pro3 in attenuating anti-atherogenic action without affecting HbA1c suggests that the enhancement of active GIP by DPP-4 inhibition suppresses atherosclerosis through direct action." (PMID 23967137, 2013). "Then, more recently, we found that a DPP-4 inhibitor, an enhancer of endogenous GLP-1 and GIP, prevented the development of atherosclerosis in the same animal model." (PMID 22536426, 2012). "Consistent with our experience in an earlier study with nondiabetic Apoe−/− mice, our current result confirmed that chronic GIP infusion suppresses the progression of atherosclerosis in diabetic Apoe−/− mice." (PMID 22536426, 2012). "We know that GIPR mediated this anti-atherogenic effect, because co-infusion of GIPR antagonist abolished the GIP-induced suppression of atherosclerosis." (PMID 22536426, 2012). "We recently reported that glucose-dependent insulinotropic polypeptide (GIP) prevents the development of atherosclerosis in apolipoprotein E-null (Apoe−/−) mice." (PMID 22536426, 2012).
atherosclerosis (continued). "As such, we were confident in surmising that the suppressive effect of GIP against atherosclerosis weakens in a diabetic condition." (PMID 22536426, 2012). "In 2011, our group reported that GLP-1 and glucose-dependent insulinotropic polypeptide (GIP), two native incretins, elicited anti-atherogenic effects in apolipoprotein-E-null (Apoe−/−) mice, an animal model of atherosclerosis." (PMID 22536426, 2012). "Some studies suggest that GIP may have beneficial effects in reducing atherosclerosis by affecting macrophage infiltration and lipid deposition." (PMID 39493783, 2024). "GLP-1, GIP, and incretins-based therapies may improve the atherosclerotic burden through the regulation of steps involved in atherosclerosis progression." (PMID 36834796, 2023). "In brief, GIP might have an indirect role in atherosclerosis, via the regulation of macrophage-driven inflammation and foam cell formation, vascular smooth muscle cell proliferation and arterial remodelling." (PMID 37592302, 2023). "In mouse models of atherosclerosis, GIP produced relevant changes in atheroma lesions." (PMID 36145148, 2022). "However, it should be noted that although the association of GLP-1 with atherosclerosis and CAD in animals and humans has been well established, for GIP, this issue has been studied in animal models, but for humans the evidence is poor." (PMID 35205155, 2022). "In studies conducted in animal models and in the context of atherosclerosis, the activation of GIP has favored the reduction of plaque formation and macrophage foam cells, the increase in plaque stability, the reduction of formation plaque and foam cell formation of macrophages." (PMID 33924893, 2021). "However, given the fact that GIP suppressed the atherosclerosis and restenosis in diabetic mice, beneficial cardiovascular effects of GIP are likely to be preserved, at least partly, in diabetic conditions." (PMID 32098413, 2020). "We recently reported that GIP infusion remarkably suppressed the development of atherosclerosis in STZ-induced diabetic Apoe−/− mice, and GIP suppressed macrophage foam cell formation obtained from the diabetic mice though GIPR was mildly down-regulated in the macrophage." (PMID 23967137, 2013). "However, the effect of GIP on macrophage foam cell formation, a crucial step of atherosclerosis, remains largely unknown." (PMID 34356896, 2021). "However, it remains unclear whether GIP infusion at the physiological dose suppresses or promotes atherosclerosis in animal models." (PMID 32098413, 2020). "However, it remains unclear whether the inhibition of physiological levels of GIP can result in the suppression of atherosclerosis in vivo." (PMID 32098413, 2020). "For the future, we would like to recognize GIP and GLP-1 as widely implemented into clinical practice as new biomarkers of atherosclerosis and coronary artery disease." (PMID 35205155, 2022). "The presented manuscript contains the most current and extensive summary of the role of the most predominant gastrointestinal hormones—GIP and GLP-1 in the pathophysiology of atherosclerosis and coronary artery disease both in animals and humans." (PMID 35205155, 2022). "In this review, we have presented the most extensive summary of the role of the most predominant gastrointestinal hormones—GIP and GLP-1—in the pathophysiology of atherosclerosis and CAD both in animals and in humans." (PMID 35205155, 2022). "This review aims to comprehensively discuss the impact of GIP and GLP-1 on atherosclerosis and CAD and its potential therapeutic implications." (PMID 35205155, 2022). "The impact of GIP on calcium signaling pathways, leading to the production of endothelin-1 (ET-1) and osteopontin (OPN), requires further investigation to understand its influence on endothelial cell function and atherosclerosis development." (PMID 39493783, 2024).
atherosclerosis (continued). "Therefore, in the present study, we investigated the effect of GIP on AGE-induced macrophage foam cell formation, an initial step of atherosclerosis." (PMID 39273671, 2024). "Tirzepatide, with a dual activity target GIP and GLP1 receptor, may have consequences for preventing or mitigating atherosclerosis due to its impact on GIPR activity." (PMID 38987789, 2024). "However, whether and how GIP could inhibit the AGE-induced foam cell formation of macrophages, an initial step of atherosclerosis remains to be elucidated." (PMID 39273671, 2024). "However, overall effects of GIP at pharmacological concentrations are likely to be protective against atherosclerosis both in non-diabetic and diabetic conditions in vivo." (PMID 32098413, 2020).